COMT (catechol-O-methyltransferase)
Diseases named in the same sentence as COMT in open-access papers (continued):
Sharing a sentence is not in itself a finding about the gene and the disease.
schizophrenia (continued). "Studies further support this regulatory mechanism by demonstrating that both miR-34a and miR-30a-5p suppress COMT gene expression in cellular models of schizophrenia." (PMID 40779062, 2026). "Several studies have evaluated the efficacy of catechol-O-methyltransferase (COMT) in disorders such as schizophrenia, DB, Parkinson’s disease, DDM, ADHD, addictions, and in OCD." (PMID 40430486, 2025). "Studies in schizophrenia support that hypomethylation of the COMT promoter increases COMT activity and enhances dopamine degradation in the prefrontal cortex." (PMID 41234420, 2025). "Gene–environment interactions contribute to the risk of schizophrenia and co-occurring substance use disorders, with BDNF, catechol-O-methyltransferase (COMT), and protein kinase B (AKT) being the most studied genes linked to both conditions." (PMID 40282201, 2025). "Several natural and synthetic COMT inhibitors have been developed to increase the available monoamine neurotransmitters for therapy for PD, depression, and schizophrenia." (PMID 40243512, 2025). "Schizophrenia and OCD share several gene polymorphisms (e.g., CACNA1C, COMT, and 5-HTTLPR), but schizophrenia still possesses other genetic polymorphisms distinct from those seen in OCD." (PMID 38814466, 2024). "The aim of this study was the identification of a specific miRNA that has a crucial regulatory role for COMT in schizophrenia." (PMID 38427212, 2024). "Genetic variants of the DTBPN1 gene associated with reduced dysbindin-1 protein (Dys) expression negatively impact cognitive functions in schizophrenia through a functional epistatic interaction with Catechol-O-methyltransferase (COMT)." (PMID 38532008, 2024). "This study aimed to analyze the possible association of miR-30a-5p, miR-30e-5p, and miR-34a-5p identified as potential candidate miRNAs in schizophrenia, with the COMT gene." (PMID 38427212, 2024). "In contrast, DRD3 gene hypermethylation is associated with decreased expression, and dysregulated methylation of COMT and DRD3 genes is linked to both schizophrenia risk and sex-specific differences." (PMID 39678047, 2024). "Due to its genomic location and its function in dopamine catabolism, COMT is considered to be a strong candidate gene that has received the most attention for schizophrenia and is promising for treatment response." (PMID 38427212, 2024). "This study adds to previous knowledge showing the implication of COMT rs4680 in schizophrenia-related cognitive impairments, its relationship with sex, and Dys gene expression in humans during adulthood." (PMID 38532008, 2024). "In patients with schizophrenia, the 5mC levels of the COMT gene are elevated, resulting in a significant increase in mRNA expression." (PMID 38203806, 2024). "The current study examined the relation between the genetic polymorphisms of COMT rs4680, NRG1 rs35753505, NRG1 rs3924999, and treatment response to risperidone in patients with psychosis from the schizophrenia spectrum." (PMID 39062492, 2024). "Their results indicate that, compared to healthy individuals, subjects with schizophrenia have a significantly lower relative expression of COMT mRNA, while its expression is increased in individuals with bipolar disorder." (PMID 36830773, 2023). "So, a gender-specific association of certain dopaminergic genes, such as catechol-o-methyltransferase (COMT) and mono-amino-oxidase (MAO), with schizophrenia was suggested." (PMID 37834018, 2023). "While there have been relatively few studies of EBDM in phenotypic models, motivational deficit in healthy ageing as well as a catechol-o-methyltransferase (COMT) model of schizophrenia in mice has been reported." (PMID 37474757, 2023). "COMT is one of the most researched genes in case of schizophrenia and its relation with cognition has been studied." (PMID 36692676, 2023).
schizophrenia (continued). "Gene-associated studies have shown a possible relationship between variants of genes related to dopamine signallings, such as catechol O-methyltransferase (COMT), monoamine oxidase (MAO), and dopamine transporter (SLC6A3), and the risk of schizophrenia." (PMID 36979236, 2023). "Ni and colleagues compared the levels of COMT gene expression in healthy individuals and individuals diagnosed with schizophrenia, bipolar disorder and depression." (PMID 36830773, 2023). "Meta-analysis has shown that COMT gene which is responsible for schizophrenia like symptoms, is located at the chromosome 22q11.2." (PMID 36692676, 2023). "For example, participants with schizophrenia who received atypical antipsychotics, most often risperidone, had lower incidence of COMT DNA methylation than patients on typical antipsychotics." (PMID 37510262, 2023). "The expression of COMT mRNA was homogenous across cortical layers, whereas patients with schizophrenia had a lower level in the superficial layers and higher in the intermediate/deep layers." (PMID 36833173, 2023). "Recently, an association study in Mexican schizophrenia patients related the single-nucleotide polymorphism A-241G of the DRD2 gene and the Met/Met allele of COMT and Ser/Gly allele of DRD3 genes with resistance to treatment." (PMID 36979877, 2023). "Our findings demonstrated sex-specific associations of COMT high-activity rs4680 and rs4818 variants and haplotype combinations with mostly lower severity of several individual PANSS symptoms in patients with schizophrenia." (PMID 37510262, 2023). "The COMT gene has long been considered a candidate gene for schizophrenia because it degrades dopamine and individuals with schizophrenia have increased dopamine levels." (PMID 35590332, 2022). "There is a strong correlation between schizophrenia and gene mutation in the transmethylation enzyme such as MAT, Met synthase, methylenetetrahydrofolate reductase, catechol-O-methyltransferase, and DNA methyltransferase." (PMID 35055113, 2022). "Support for a hypodopaminergic trait was similarly found in a study that examined the relationship between catechol-O-methyltransferase (COMT) polymorphism and premorbid cannabis use in Turkish male patients with schizophrenia." (PMID 36135314, 2022). "COMT is involved in the metabolism of dopamine, a key neurotransmitter in schizophrenia pathophysiology." (PMID 33825996, 2021). "One of the most studied genes for its interaction with cannabis and impact on schizophrenia development is COMT." (PMID 34946799, 2021). "Another research was done in 2020 to study the effect of rs1076560 (dopamine receptor D2 or DRD2) and rs4680 (COMT Val158Met) on tardive dyskinesia and cognition in schizophrenia patients." (PMID 34725583, 2021). "It is thought that a decreased COMT methylation in schizophrenia patient leads to an increased expression and thus increased activity of COMT protein." (PMID 34831111, 2021). "The top three phenotypes for COMT gene were 22q11 microdeletion with velocardiofacial syndrome phenotype, schizophrenia, and aggression." (PMID 34315992, 2021). "The COMT protein is responsible for the degradation of catecholamine like dopamine and in schizophrenia this process is disrupted." (PMID 34831111, 2021). "The study found that IL-10 did not have any effect on cognition if measured alone; however, COMT alone had an impact on language and schizophrenia." (PMID 34725583, 2021). "In a research study done in 2021, 98 patients with recent-onset schizophrenia were administered aripiprazole long-acting injectable (LAI) for three months, and genetic polymorphism of COMT along with two other genes was determined." (PMID 34725583, 2021).
schizophrenia (continued). "Although a recent meta-analysis could not detect significant sex-related difference in the functional effect of the COMT rs4680 genotype, our findings suggest that sex should be taken into account in future studies focusing on the association between COMT polymorphisms and symptoms in schizophrenia." (PMID 34287249, 2021). "There is evidence of an increased methylation in the promoter regions of catechol-O-methyltransferase (COMT) in patients with schizophrenia." (PMID 34831111, 2021). "Antipsychotic drugs target primarily dopaminergic system which makes catechol-O-methyltransferase (COMT) an interesting target in studies searching for treatment response predictors in schizophrenia." (PMID 32572118, 2020). "The efficacy of antipsychotic drugs in patients with schizophrenia has been shown to be related to catechol-o-methyl transferase (COMT) genotype at the 158th codon, where a valine-to-methionine substitution (rs4680) is common." (PMID 30712251, 2020). "Subsequent positive results have been seen in studies considering the combined interaction between COMT genotype, cannabis use, and history of childhood abuse and subsequent schizophrenia." (PMID 31661851, 2019). "In these samples, they detected a protective effect against schizophrenia of the COMT Val/Met heterozygous genotype (OR = 0.75, CI95 = 0.62–0.91, p = 0.003)." (PMID 31156495, 2019). "We investigated the associations of rs4680 COMT, rs6280 DRD3, and rs7322347 5HT2A with youth-onset schizophrenia in the Russian population in a case–control study, and the role of the genotype in the severity of clinical features." (PMID 31798476, 2019). "COMT-met genotype patients with schizophrenia respond more strongly than COMT-val genotype patients to dopamine antagonists." (PMID 30894870, 2019). "Genotype frequencies of rs6280 (DRD3), rs4680 (COMT), and rs7322347 (5HT2A) in the control and youth-onset schizophrenia groups." (PMID 31798476, 2019). "We decided to investigate the association of rs4680 COMT, rs6280 DRD3, and rs7322347 5HT2A with youth-onset schizophrenia in a homogenous Russian population, because of their prominence in the literature." (PMID 31798476, 2019). "Given its role in catechol catabolism, COMT represents an important drug target for treating neurological disorders such as Parkinson’s Disease and schizophrenia." (PMID 30428636, 2018). "Despite the fact that a number of investigations concerning associations between COMT and GAD1 genes with schizophrenia have been performed, the conclusions from these reports are somewhat open to debate." (PMID 29429137, 2018). "In line with our findings, in the large Shanghai cohort of 995 Chinese patients with schizophrenia, C carriers of the COMT rs4818 had more frequently poor response to quetiapine." (PMID 30018555, 2018). "Female patients with schizophrenia, carriers of the COMT rs4680 AA genotype, had smaller volumes of caudate, putamen, and pallidum, while male patients, homozygous for the Met allele showed higher or similar subcortical volumes compared to other groups." (PMID 30018555, 2018). "We aimed to estimate the role of two talent genes: DAOA in neurotransmission of glutamate and COMT in neurotransmission of dopamine to guide the treatment of schizophrenia and bipolar disorder." (PMID 30719257, 2018). "The majority of studies addressing G × E interactions in schizophrenia spectrum phenotypes and BD have focused on the effect of variation in the COMT, BDNF, and FKBP5 genes, showing interactions with cannabis use and childhood trauma." (PMID 28822116, 2018). "The results showed that three of these positions were associated with both diseases and one position was associated with bipolar I. Thus, there are possibilities for DAOA and COMT genes variations to be involved in schizophrenia and bipolar I disorders." (PMID 30719257, 2018).
schizophrenia (continued). "Due to its genomic location and its function in the catabolism of dopamine COMT is considered as a strong candidate gene for schizophrenia (Acar, Sözen, Gözükara, Orman, & Kartalci, 2015)." (PMID 30165727, 2018). "In terms of genetic-structural MRI studies, “patients with schizophrenia are found to have reductions in the frontal, temporal, parietal cortices, and limbic regions, which are associated with BDNF, COMT, and neuregulin-1 (NRG1) genes”." (PMID 30349492, 2018). "The performance of patients with schizophrenia provides an interesting counterpoint to the combined effect of COMT and DAT." (PMID 30618672, 2018). "In contrast to our data, among 117 patients with schizophrenia of the southern Indian origin, the COMT haplotype C-A (rs4818-r4680) was observed more often in responders to risperidone, compared to non-responders." (PMID 30018555, 2018). "DAOA and COMT genes are two potential candidates for involvement in schizophrenia and bipolar disorder molecular mechanisms." (PMID 30719257, 2018). "Inhibition of COMT can increase neurotransmitter levels, which provides a means of treatment for Parkinson’s disease, schizophrenia and depression." (PMID 27981425, 2017). "Early candidate genes studied in relation to brain phenotypes included the sodium-dependent serotonin transporter gene (SLC6A4) in individuals with anxiety and depression and the catechol-O-methyltransferase gene (COMT) in individuals with schizophrenia." (PMID 29179742, 2017). "The methylation of the catechol-O-methyltransferase (COMT) gene promoter is also a candidate for the molecular pathology of schizophrenia." (PMID 28387726, 2017). "In agreement to previous studies in healthy subjects, patients with schizophrenia and genetically modified mice, COMT-dependent effects were selective to executive functions." (PMID 28556830, 2017). "Numerous studies have suggested a genetic predisposition to schizophrenia, and many genes, including DISC1, catechol-O-methyltransferase (COMT), neuregulin 1 (NRG1), and DTNBP1, have been identified as candidate susceptibility genes." (PMID 28937620, 2017). "For example, Catechol-O-methyltransferase (COMT) gene, which is implicated in schizophrenia has a SNP, Val158Met (rs4680) that is associated with differential COMT expression across regions of the brain during the course of the illness." (PMID 29047346, 2017). "COMT has implications in many neurological and psychiatric disorders like Parkinson's disease, chronic fatigue, pain response, schizophrenia, and bipolar disorders." (PMID 28066248, 2016). "In schizophrenia patients, COMT rs4680GG homozygous patients (with lower dopamine signaling) have a significant GMV reduction in the SN regions compared to A-allele carriers (with higher dopamine signaling)." (PMID 26498330, 2016). "COMT is therefore a potentially important player in linking certain cognitive and neuroanatomical symptom domains of depression and schizophrenia to the DA system." (PMID 25762938, 2015). "Several studies reported the association between PPI in schizophrenia and HT2AR, COMT, NRG1 and RELA, which also directly or indirectly influence glutamatergic signaling." (PMID 25768306, 2015). "The influence of sex on the involvement of COMT genotype in schizophrenia vulnerability has been reported in several studies." (PMID 25722988, 2015). "Consistent with this possibility, MTHFR C677T has an epistatic effect with COMT Val158Met, on dorsolateral prefrontal fMRI activation during working memory performance in schizophrenia." (PMID 25010186, 2014). "While most of the research on COMT genotypes and schizophrenia has been focused on the impairments associated with the Val variant, emerging lines of evidence have also pointed to the possibility that the Met-variant may predispose schizophrenia patients to aggression and violence." (PMID 24639636, 2014).
schizophrenia (continued). "These included genes linked to bipolar disorders and schizophrenia, such as CACNA1C and DISC1, as well as the COMT gene." (PMID 24409157, 2014). "Patients with 22q11 deletion syndrome, which disrupts DA-related genes (e.g., catechol-O-methyltransferase, COMT) among others have an increased risk for neuropsychiatric disorders, including schizophrenia-like psychosis, autism, and anxiety disorders." (PMID 24391541, 2013). "Given the heritability of working memory deficits, several studies investigated the association between processing efficiency and catechol-O-methyltransferase (COMT), a known schizophrenia risk gene, during a working memory task." (PMID 25379242, 2013). "Ohnishi and colleagues examined COMT Val158Met in relation to brain structure in a sample of 76 healthy controls and 47 schizophrenia patients." (PMID 22479488, 2012). "By contrast, in the prefrontal cortex, that mediates the cognitive functions, which are impaired in schizophrenia, dopamine levels are sensitive to COMT levels." (PMID 23762769, 2012). "COMT inhibitors are licensed as adjunctive therapy for Parkinson's disease and are under investigation in schizophrenia and other neuropsychiatric conditions." (PMID 22364739, 2012). "The findings are of translational relevance, because COMT inhibitors are used in the adjunctive treatment of Parkinson's disease and are under evaluation in schizophrenia and other disorders." (PMID 22364739, 2012). "Due to its involvement in the catabolic clearance of dopamine and its location in the 22q11 microdeletion area, COMT is a plausible candidate gene for schizophrenia." (PMID 23762769, 2012). "Overall, the majority of research on BDNF has focused on memory function and for COMT on measures of executive skills and working memory in healthy controls and individuals with neuropsychiatric disorders (e.g., schizophrenia-spectrum and bipolar disorders)." (PMID 23087644, 2012). "Our results for the relationships of COMT polymorphism to neurocognition in AUD were consistent with findings in normal controls and individuals with schizophrenia-spectrum disorders." (PMID 23087644, 2012). "Our study provides further support for the importance of the COMT in alcohol dependence in addition to schizophrenia." (PMID 22208661, 2011). "It is well established that COMT is a strong candidate gene for substance use disorder and schizophrenia." (PMID 22208661, 2011). "COMT promoter methylation deficits have been described in schizophrenia, with concordant increases in COMT expression." (PMID 21217836, 2010). "In our results, the COMT Val158Met genotype frequency was founded by 53.9% for GG (Val), 38.6% for GA (Val/Met) and 7.5% for AA (Met) in schizophrenia." (PMID 21217836, 2010). "The present findings offer an additional facet to COMT's biology that has new, broad and potentially important implications for cancer biology and schizophrenia via its interaction with AKT1." (PMID 20520724, 2010). "In this study, we evaluated the association between functional polymorphisms in COMT and MTHFR and schizophrenia risk with a case-control study in a Korean population." (PMID 21217836, 2010). "Our findings provide a potential mechanism for the impact of COMT on NRG1-induced adhesion and migration and also possibly for the association of these genes with schizophrenia and cancer." (PMID 20520724, 2010). "Common genetic SNPs in two genes, encoding catechol-O-methyltransferase (COMT) and methylenetetrahydrofolate reductase (MTHFR), which are interconnected with COMT gene regulation, have been reported to contribute to schizophrenia risk." (PMID 21217836, 2010). "Catechol-O-methyltransferase (COMT), a common functional polymorphism, has been related to executive performance in young healthy volunteers, old subjects and schizophrenia patients." (PMID 21029471, 2010).